MMP2 (matrix metallopeptidase 2)
Diseases named in the same sentence as MMP2 in open-access papers (continued):
Sharing a sentence is not in itself a finding about the gene and the disease.
tumor (continued). "In particular, MMP14 can control the formation of invasive pseudopodia, while MMP2 and MMP9 play a key role in tumor invasion." (PMID 37686118, 2023). "M2 macrophages secrete various cytokines such as MMP-9, MMP-2, MMP-12,VEGFIL-8, IL-1 and fibroblast growth factor to induce tumour angiogenesis and a worsened prognosis." (PMID 37742025, 2023). "Through the remodeling of the extracellular matrix, MMP-2 and MMP-9 are involved in tumor invasion and metastasis." (PMID 37516013, 2023). "Meanwhile, the results of immune-histochemical staining showed that MMP-2 and MMP-9 were abundantly expressed in the left atrium tumor-like lesions of αMHC-Cre mice." (PMID 36834504, 2023). "MMP-2 and MMP-9 are two important matrix metalloproteases expressed in tumor cells, which promote carcinogenesis by destroying the extracellular matrix type IV collagen at the basement membrane during cancer invasion and metastasis." (PMID 37259418, 2023). "Through PPI and CT network analysis, 17 important targets were identified, and 2 pivotal target genes, MMP2 and MMP9, were validated as upregulated in GC and involved in the tumor immune microenvironment." (PMID 37565919, 2023). "In summary, ERIANIN acts on the Wnt and ERK1/2 pathways and their downstream genes, MMP-2 and MMP-9, to inhibit tumor metastasis, as shown in." (PMID 37187758, 2023). "Esculetin’s antiangiogenic action in LM8 cells have been due to the inhibition of MMP-2, TGF-β1 and VEGF productions at tumor sites." (PMID 37560476, 2023). "Compared with the CTX group, the expression levels of MMP-9, MMP-2, VEGF, bFGF, Bax, and Bcl-2 in tumor tissues were reversed by 47%, 72%, 49%, 60%, 57%, and 48%, respectively, after high-dose GFG combined with CTX treatment." (PMID 37049720, 2023). "It has been found that MMP-2 and MMP-9 are highly expressed in a variety of tumor cells, including those in gastric, breast, prostate, rectal, lung, and ovarian cancers." (PMID 36986636, 2023). "The increased MMP-2, MMP-9 and waveform proteins, as well as the decreased E-calmodulin in tumor cells, tend to promote the process of epithelial–mesenchymal transition (EMT), thus favoring tumor expansion into adjacent tissues." (PMID 37367063, 2023). "MMP2, also known as gelatinase A, contributes to the remodeling ECM, especially in the normal bone, but also during development, wound healing, angiogenesis, and in disease, and tumor invasion." (PMID 37445827, 2023). "Increased cell migration and invasion are promoted by interactions between the tumor cell surface epidermal growth factor (EGF) receptors and its ligand EGF via upregulating MMP-2 expression." (PMID 37798646, 2023). "These nanoparticles reached the targeted site through EPR effect and were triggered by MMP-2 to release the PTX-SS-COOH first, then conjugated PTX was released at tumor site." (PMID 36850121, 2023). "Three target MMP enzymes were selected for the MMP inhibition assay, the collagenase MMP-1, and the gelatinases MMP-2 and MMP-9, which are upregulated in a number of tumor types." (PMID 37108137, 2023). "COL12A1+ fibroblasts highly expressed MMP2, MMP14, and TGFB1, which are related to tumor cell invasion and ECM degradation." (PMID 37430270, 2023). "MMP-2 and MMP-9 belong to the gelatinase class, and in cancer, they play important roles in angiogenesis, tumor growth, invasion, and metastasis." (PMID 38003553, 2023). "We further analyzed ACC Meso-1 xenograft tumor tissues treated with the cullin inhibitor, pevonedistat, which targets protein neddylation, and observed the downregulation of human TGF-β1 and MMP2." (PMID 37686215, 2023). "Matrix metalloproteinase (MMP)-2 and MMP-9 degrade the extracellular matrix and basement membrane and play key roles in tumor invasion and metastasis." (PMID 37006921, 2023).
tumor (continued). "The role of MMP-2 and MMP-9 in the degradation of ECM significantly contributes to tumor invasion and the aggressiveness of GBs, while the aberrant expression of VEGFA is suggested to drive angiogenesis and tumorigenesis." (PMID 37190125, 2023). "MMP-2 and MMP-9 are involved in the remodeling process of the extracellular matrix, increasing its secretion during invasion and tumor metastasis." (PMID 38137922, 2023). "Working through the SDF-1/CXCR4 pathway, SDF-1 increased MMP-2/MMP-9 production and led to an increased tumor invasiveness." (PMID 36980785, 2023). "AXL tyrosine kinase promotes tumor progression through AKT/GSK-3β/β-catenin signaling, β-catenin nuclear-translocation-induced SNAIL transcription, and MMP-2 and MMP-9 activation." (PMID 37046676, 2023). "Recent studies have shown that STAT3 signaling can promote angiogenesis by regulating VEGF-A and MMP2 expression, while inhibition of STAT3 activation can inhibit tumor angiogenesis and growth." (PMID 37576403, 2023). "In these studies, MAFs are the main component of the tumour stroma and can remodel the extracellular matrix (ECM) by expressing factors such as fibronectin, TGFβR2, collagen 1, and matrix metalloproteinase-2 (MMP2)." (PMID 37372146, 2023). "Silencing of AKR1B10 in these tumor cells downregulated MMP2 and MMP9 expression, suppressing both in vitro and in vivo tumor cell extravasation across the BBB." (PMID 37688612, 2023). "Taken together, macrophage-derived MMP-9 and MMP-2 were closely related to the rupture of the FC of HCC and subsequently led to the migration and invasion of the tumor cells through the ruptured area of FC to the para cancer." (PMID 36918768, 2023). "The suppression of these signaling pathways also decreased MMP2 and MMP9 expressions, which are the critical markers of tumor metastasis." (PMID 37367670, 2023). "Among these, MMP-2 is expressed most frequently when tumor cells undergo invasive behavior, while MMP-9 is expressed most frequently when tumor cells undergo metastatic behavior." (PMID 36976205, 2023). "In the process of tumor progression, MMP-2 and MMP-9 can mediate the invasion of tumor cells into the basement membrane through the degradation of collagen IV, thus resulting in tumor metastasis and diffusion." (PMID 36906534, 2023). "The researchers examined the relationship between MMP-2 levels and clinicopathological characteristics of PTC, including tumor size, lymph node involvement, and distant metastasis." (PMID 38089632, 2023). "miR-4510 demonstrated its tumour suppressor effects by targeting and inhibiting apolipoprotein C-II (ApoC2) expression, and also decreased the activity of AKT, ERK1/2, MMP2 and MMP9." (PMID 36765536, 2023). "MMP2 and MMP3 can degrade multiple components of basement membrane and extracellular matrix, and MMP9 is able to induce tumor cells to infiltrate and metastasize into adjacent normal tissues through the injured basement membrane." (PMID 37100464, 2023). "EDX suppressed elevated plasma levels of IL-6, MMP-2, TF, and PAI-1 and elevated tumor tissue levels of PAR2, STAT3, cyclin D1, and Ki67 in Colon26-inoculated mice." (PMID 36751299, 2023). "Gallic acid and Caffeic acid block the processes of angiogenesis and tumor growth via protection of the tumoricidal efficacy of M1 macrophages and inhibition of proangiogenic factors, particularly VEGF, MMP-2/9, and cyclooxygenase-2 (COX-2) activity." (PMID 37560476, 2023). "The upregulation of MMP-2, MMP-9 and Vimentin and the inhibition of E-cadherin in tumor cells will promote EMT and contribute to tumor invasion." (PMID 37367063, 2023). "Overexpression of MMPs, including MMP2 and MMP13, promotes tumor progression mainly through degradation of extracellular matrix components." (PMID 38273855, 2023).
tumor (continued). "Usually, the pH value of a tumor tissue is 6.3–6.8, while higher concentrations of various biological substances are detected in cancer cells such as GSH and matrix metalloproteinase 2 (MMP2) as well as active oxidative species (ROS)." (PMID 36986652, 2023). "First, the enzymatic breakdown of the peptide sequence, GALGLPG (GG), in the TME by MMP-2 and MMP-9 overexpression permits tumor-specific accumulation and retention of BLPNs." (PMID 37144580, 2023). "Matrix metalloproteinase-2 (MMP-2)- and MMP-9-sensitive materials respond to the tumor microenvironment by overexpressing MMP-2 and MMP-913." (PMID 37144580, 2023). "The relationship between TGF- β1 and EMT process which is essential for tumor cell progression and migration can be explained through the stimulatory effect of TGF- β1 on matrix metalloproteinase (MMP) such as MMP-2 and MMP-934." (PMID 37993664, 2023). "The peptide linker was used to cleave in response to the upregulated MMP-2 in the tumor microenvironment, thus exposing a positive charge via PEG-deshielding and enhancing liposomal uptake by tumor cells/vasculature." (PMID 36910721, 2023). "MMP2 and MMP9 are gelatinases of the MMP family, which degrade extracellular matrix and are involved in tumour invasion, metastasis and immune surveillance." (PMID 36457281, 2023). "CRC cells with high expressions of miR-206 and miR-133b exhibited the downregulation of MMP2 and VEGFA protein levels, indicating a potential influence on the tumor microenvironment matrix." (PMID 38069061, 2023). "Two matrix metalloproteinases (MMPs) MMP2 and MMP9 are the endopeptidases involved in ECM remodeling, EMT, and tumor cell invasion." (PMID 37963859, 2023). "The high expression of MMP-2 and MMP-9 in cancerous tissues has been correlated with tumor cell matrix degradation, invasion, and migration." (PMID 37964204, 2023). "At the same time, MMP2 and MMP9, and other MMPs can be regulated by activated AKT, and tumor cells with excessive activation of the PI3K/AKT signaling axis are more likely to undergo EMT." (PMID 37686118, 2023). "AS-IV upregulates the levels of Ki67, MMP-2, and MMP-9 by regulating the MAPK/ERK signaling pathway, which further results in the suppression of tumor cell growth, migration, and invasion abilities." (PMID 37063281, 2023). "The growth of solid tumours depends on the formation of new blood vessels (angiogenesis), affecting the size of the tumour and the process of metastasis, which are closely related to the levels of VEGF, MMP-2, and MMP-9." (PMID 37446252, 2023). "MMP2 and MMP9 are molecular markers of tumor invasion and metastasis, including GC, and inhibition of their expression reduces the invasion and migration capabilities of GC cells 22-24." (PMID 36778127, 2023). "Matrix metalloproteinases MMP1, MMP2, MMP3 and MMP9, which are involved in extracellular matrix (ECM) remodeling and promotion of tumor cell migration and invasion, were also significantly increased (p < 0.0001) in metastatic cell lines compared to PM cells." (PMID 37047539, 2023). "An increase in the levels of MMP-2 and MMP-9 has been described in the irradiation of various tumours." (PMID 38203696, 2023). "Matrix metalloprotein-2 (MMP-2) and Matrix metalloprotein-9 (MMP-9) are markers of tumor invasion and metastasis." (PMID 37187758, 2023). "MMP-2 and MMP-9 activity was also analysed between xenograft tumours derived from “double-hit” and “single-hit” cell lines." (PMID 38203696, 2023). "Correlation analysis displayed that the metastatic rates of the tumor cells were positively correlated with the expression of ANKRD49, MMP-2, MMP-9, p-JNK, p-c-Jun or p-ATF2." (PMID 37964204, 2023). "MMP2 and MMP9 are well-known tumor metastasis markers, while PTEN is a well-characterized tumor suppressor gene that plays a major role in the metastasis of GC 15-17." (PMID 36778127, 2023).
tumor (continued). "To achieve the effective inhibition of tumor growth and metastasis, in this study, we proposed a smart transformable peptide‐conjugated probe DMFA with MMP‐2 cleavage‐induced morphological change." (PMID 36793151, 2023). "In this study, we found that diHEP-DPA significantly inhibited the infiltration of TAMs and decreased the secretion of MMP2, MMP9, VEGF, IL-6, and TNF-α in tumor tissue." (PMID 36827121, 2023). "Notably, compared with the IR780 + 1-MT + IL-15 + L group, the NIL-IM-Lip+L group exhibited better immune cell regulation in the TLIME, verifying that the pH/MMP2/temperature triple-sensitive immunomodulatory nanoinducer NIL-IM-Lip could accumulate in tumour tissues and be directed to the LNs." (PMID 37076492, 2023). "MMP2 and MMP9 are overexpressed in many tumors, and high MMP2 and MMP9 levels promote tumor metastasis and progression." (PMID 37521428, 2023). "IL-1α in bladder cancer cell CM induces the release of IL-8, HGF, MMP-2, GM-CSF and monocyte chemotactic protein (MCP)-1 by CAFs, which, in turn, reciprocally induce migration and invasion in the tumor cells through MCP and HGF." (PMID 37046676, 2023). "Meanwhile, the expression of PCNA, VEGF, MMP‐2 and MMP‐9 was dramatically reduced in tumour‐bearing mice treated with PA in comparison with the vehicle group." (PMID 37038620, 2023). "The upregulation of N-cadherin, Vimentin and MMP2 facilitates the process of EMT and contributes to the metastasis of tumor cells." (PMID 37904179, 2023). "MMP2 activation will lead to degradation of the ECM, EMT, and further promote tumor invasion, angiogenesis and metastasis." (PMID 35177031, 2022). "The LyP-1-functionalized nanosystem targeted tumor lymphatics, instigated nuclear rupture and mitochondrial distortion, and decreased cell proliferation and migration with inhibition of VEGF-C and MMP2 expression." (PMID 35337150, 2022). "In oral squamous cell carcinoma, TGF-β1 facilitates MT1-MMP-mediated MMP-9 activation and stimulates invasion of the tumor in collaboration with MT1-MMP and MMP-2." (PMID 35204054, 2022). "One smart DDS for delivery of TCS into tumor cells has included lower molecular weight protamines (LMWPs), which mainly consist of arginine (VSRRRRRRGGRRRR), matrix metalloproteinase-2 (MMP-2) substrate (MSP) peptide, and PEG." (PMID 35744957, 2022). "Tumor metastases begin with basement membrane degradation by matrix metalloproteinases (MMPs), such as MMP2 and MMP9, followed by tumor extravasation and dissemination, and finally colonization in new lesions." (PMID 36612163, 2022). "On the contrary, CXCR4 overexpression increased the tumor-derived DNA expression of ERK1/2 and MMP2/9, increased the proliferative and migratory activities of SK-Hep1 cells, and reduced apoptosis." (PMID 35860597, 2022). "A variety of MMPs, including MMP-2, MMP-9 and MMP-14, can degrade the basal layer of capillaries and promote exosmosis of tumor cells." (PMID 36776395, 2022). "After the xenograft tumour was established in mice, the tumour volume was determined and the expressions of METTL3, miR‐589‐5p, MMP‐2, TIMP‐2, E‐cadherin, N‐cadherin and Vimentin in tumour tissue were detected by RT‐qPCR and Western blotting." (PMID 35348293, 2022). "Studies have suggested that astrocytes can secrete matrix metalloproteinase (MMP)-2 and MMP-9, remove matrix components on the surface of tumor cells and the surrounding matrix, and promote the invasion and metastasis of tumor cells." (PMID 36338717, 2022). "The results showed that MMP2 and MMP9 were significantly highly expressed in MRTK tumour tissues compared to adjacent cancerous tissues, and MMP2 and MMP9 were equally highly expressed in G401 cells compared to control HEK293T cells." (PMID 36408277, 2022). "Human thyroid carcinoma tissue has also been reported to express MMP-1, MMP-2, and MMP-9 and these MMPs were localized in tumor cells and/or in the fibroblasts adjacent to or close to the invading tumor cells." (PMID 36551933, 2022).
tumor (continued). "Among them, MMP-2 and MMP-9 are the major proteinases contributing to extracellular matrix degradation in the process of tumor cell migration." (PMID 35468097, 2022). "Although we did not detect ROS or EMT marker levels in this study, the increased levels of prometastatic molecules pro-MMP-2 and ICAM-1 indicate that PM2.5 induces tumor metastatic activity." (PMID 36185331, 2022). "rWISP-1 also blocked signaling pathway activation and the protein expression of MMP2 and MMP12 in CD326+ tumor cells and reduced the mRNA expression levels of CAF activation markers in Thy1+ CAFs." (PMID 36241874, 2022). "For example, tumor-cell-isolated EVs can upregulate the expression of vascular endothelial growth factor (VEGF) and matrix metalloproteinase 2 (MMP2) in endothelial cells, thereby stimulating angiogenesis and vascular permeability in the pre-metastatic niche." (PMID 35735488, 2022). "Western blot was applied to measure the mitigation of Mcl-1, PCNA, MMP-2, MMP-9, biomarkers of EMT process and the activation of caspase cascade, reflecting the influence of ID09 to tumor malignant biological behaviors in vivo." (PMID 35002504, 2022). "It has been reported that IL-6 can enhance tumor angiogenesis and metastasis either directly or by inducing the expression of well-known angiogenic and metastatic molecules such as VEGF, MMP2 and MMP9 in cancer cells." (PMID 35300689, 2022). "Immunohistochemical analysis of the tumour tissues showed changes in the protein expression of MMP9, vimentin, Bax, Bcl‐2, p‐p65, CDK9, MMP2, N‐cadherin and MIF." (PMID 35060345, 2022). "The cleavage of PLGVR in the existence of overexpressed MMP-2 led to DePEGylation and the revealing of the targeting peptide RGD, thus resulting in a “tumor-triggered targeting”." (PMID 35955225, 2022). "The prodrug nanovesicles accomplish favorable tumor accumulation and deep tumor penetration via MMP‐2‐mediated cleavage of the PEG corona, achieving tumor‐specific codelivery of OXA." (PMID 36344430, 2022). "Two members of secreted matrix metalloproteinases (MMPs), i.e., MMP2 (gelatinase A) and MMP9 (gelatinase B) localize at the surface of tumour cells, and can be encompassed in the group of ectoenzymes." (PMID 35158891, 2022). "An MMP-2-cleavable GPLGLAG (GG) heptapeptide spacer, was introduced into the PD7 POLY-PROTAC (namely, PGD7) to promote tumour-specific accumulation and cellular uptake of the POLY-PROTAC NPs." (PMID 35882867, 2022). "Reduced SLC2A1, ABCB1, MMP2, twist family bHLH transcription factor 1, and VEGFA expression in tumor cells; downregulation of HIF-1α." (PMID 35640930, 2022). "MMPs, like MMP-2 and MMP-9, play a role in ECM degradation and are highly expressed in carcinomas to promote tumor angiogenesis and consequent cancer cell invasion and metastases." (PMID 36185289, 2022). "In all tumor cells, levels of pro MMP-9 and pro MMP-2 remained unchanged following treatment with either CXCL12 or CXCL11 alone (100 ng/ml, 24 h) or in combination." (PMID 36539774, 2022). "EGCG inhibited the activities of MMP2 and MMP9, and promoted the expression of tissue inhibitor of MMPs (TIMp1/2) to suppress the invasion and metastasis of tumor cells." (PMID 36545470, 2022). "Matrix metalloproteinases (MMP2 and MMP9) not only release growth factors to promote the growth of tumor cells, but also promote cell shedding to facilitate the invasion and metastasis of tumor cells." (PMID 35668940, 2022). "Immune blot results showed that MMP2, MMP9, and MMP13 (migration marker proteins) expression decreased in tumor tissues of anti‐Chi3L1 antibody‐treated mice." (PMID 34861103, 2022). "M2-type TAMs can produce tumor-promoting factors such as IL-6 and VEGF, MMP-2, MMP-7 to promote angiogenesis, thereby promoting tumorigenesis.The ratio of M1/M2 TAMs varies among individuals and in different immune microenvironments." (PMID 35965533, 2022).